SOX4 (SRY-box transcription factor 4)
Diseases named in the same sentence as SOX4 in open-access papers (continued):
Sharing a sentence is not in itself a finding about the gene and the disease.
tumor (continued). "Additionally, quantitative real-time PCR analysis demonstrated that the expression of SOX4 mRNA was substantially increased in tumor tissues when compared with non-tumor tissues." (PMID 23285187, 2012). "There were almost no FGF19-expressing cells that did not also express either AXIN2 or SOX4, suggesting that FGF19 expression is a unique feature of a subset of AXIN2+, SOX4+ tumor cells." (PMID 39567523, 2024). "Various markers such as SOX4, VEGF, BDNF, and targets of the Wnt/β-catenin signaling pathway and the Notch pathway are expressed in ACC, but not equally in all tumor patients." (PMID 36835997, 2023). "WNT4 had decreased expression (logFC = −1.6), and the expression of seven mRNAs (CDK4, MAPK1, TGFB, ZEB2, AURKA, SOX4, and ADAM9) in tumor samples was not notably different from that in the group of normal tissues." (PMID 35453574, 2022). "To identify the tumor cells and non-tumor lung cells, we first mapped the expression of six genes (FOLR1, AGR3, and SFTPD for normal hung lung cells, and EPCAM, MDK, and SOX4 for cancer cells) to each cluster to identify the cell types in our study." (PMID 32549766, 2020). "For SOX4, we observed positive immunoreactivities in GBM samples with nucleus staining pattern in tumor cells but negative staining in normal brain tissues." (PMID 20419098, 2010). "Additionally, to assess the contamination of tumour cells in metastatic samples, we examined the expression of oesophageal epithelium genes (KRT5, KRT19, EPCAM and SOX4) and found almost no cells that expressed these genes." (PMID 36650114, 2023). "In the primary tumors we could not identify a correlation between morphology patterns and SOX4, possibly due to the low number of SOX4KO tumors and the severe differences in tumor growth." (PMID 34584219, 2021).
cancer (268 papers, 2007 to 2026). A tumor composed of atypical neoplastic, often pleomorphic cells that invade other tissues. "Through scRNA-Seq data, we detected high expression of SRY-box transcription factor 4 (Sox4) and Kruppel-like factor 6 (Klf6) in the C2 epithelial cell cluster, with Sox4 and Klf6 being associated with the maintenance of cancer stem cell stemness." (PMID 39774471, 2025). "Aberrant overexpression of SOX4 is also associated with the development of various types of human cancers and the maintenance of cancer cell stemness." (PMID 39107908, 2024). "Gene association and enrichment analyses showed that CD24/SOX4-centered signaling hub was associated with cancer cell metabolism, immune responses, ECM regulation, and Wnt/β-catenin pathways." (PMID 38203779, 2024). "DNAm or expression of SOX4 in mice and humans are associated with aging or age-related disease, notably cancer." (PMID 37270437, 2024). "The role of SOX4 in pan-cancer and its underlying molecular mechanism in liver hepatocellular carcinoma (LIHC) are not fully understood." (PMID 37958409, 2023). "Blast cells from B/My MPAL MRD + patients overexpressed genes such as NEAT1 and SOX4 that are associated with cancer development and pan-cancer poor outcome." (PMID 37845689, 2023). "In cancer, we and others have recently clarified that SOX4 is a master regulator of the epithelial-mesenchymal transition, an important pathological process associated with cancer and chronic inflammation which enhances the propagation of epithelial cells." (PMID 36835620, 2023). "Among the upregulated genes we noticed markers those were associated with cancer genesis and development, including SOX4, SPINK1, CEACAM6, KRT8 and KRT18." (PMID 37957625, 2023). "Two of these transcription factors have been linked to modulating TUBB3 expression in cancer, SOX4 and SOX9." (PMID 35573698, 2022). "While both are linked to neurogenesis and neuronal crest cell formation, increased SOX4 expression is also commonly linked with several forms of cancer, in particular lung cancer, and has been suggested as a driver oncogene." (PMID 35573698, 2022). "SOX4 protein is overexpressed in various malignancies such as lung, breast, and prostate cancer, and it is closely associated with cancer migration and invasion." (PMID 33923245, 2021). "Several cancer-associated signaling pathways have been implicated in the activation of SOX4, including Wnt, TNF-α, TGF-β, and hypoxia/HIF-1α signaling." (PMID 33407675, 2021). "Next, the mutation and copy number alterations of SOX4 were examined in various cancer types using the cBioPortal database (version 3.7.2, MSKCC, New York, NY, USA)." (PMID 34442467, 2021). "Increasing evidence has shown that the transcription factor SOX4 is closely associated with the development and progression of many malignant tumors." (PMID 33005101, 2020). "SOX4 gene overexpression has been reported in various human cancers including BC and is associated with tumorigenesis and cancer progression through the EMT." (PMID 31963556, 2020). "MiRNA-140 overexpression enabled increased cell death of HGC-27 cells after doxorubicin treatment, via SOX4 which has been associated with chemosensitivity in other cancers." (PMID 31979312, 2020). "SOX4 is a prominent cancer-associated transcription factor and its mRNA expression is elevated in a large number of human cancers, being part of a general human cancer-associated gene expression signature." (PMID 30507376, 2018). "Second, the anti-apoptotic function of SOX4 apparently causes resistance to anti-cancer treatement such as CRT." (PMID 26555193, 2015). "Aberrant expression of SOX4 has been identified in several human cancers, and it is often associated with the progression of cancer." (PMID 26583330, 2015). "Sex-determining region Y-box 4 (SOX4), which is a highly conserved developmental transcription factor, has been implicated in playing an important role in Wnt signaling pathway in cancers." (PMID 24188694, 2013).
cancer (continued). "Over-expression of SOX4 is associated with many cancers (including prostate) and anchorage independent growth." (PMID 21696611, 2011). "In both cohorts, a high SOX4 transcript level was significantly associated with recurrence of stage II MSS cancer and shorter recurrence-free survival." (PMID 19156145, 2009). "SOX4 has recently been identified in various cancer types and implicated in cancer initiation." (PMID 38203779, 2024). "Larger case series will be needed to understand whether constitutional CNVs involving SOX4 indeed predispose carriers to develop paediatric cancer." (PMID 38397148, 2024). "SOX4 is frequently mutated and upregulated in more than 20 cancers." (PMID 35794546, 2022). "In this work, we found that one lncRNA, annotated as CASC15 (cancer susceptibility candidate 15) and located in the neighbourhood of the SOX4 locus, could upregulate SOX4 expression in NSCLC cell lines." (PMID 33407675, 2021). "Although the amplification of SOX4 can lead to upregulation of SOX4 expression, the association between mutations of SOX4 and their gene expression with various cancer phenotypes was unknown and should be pursued in further study." (PMID 34442467, 2021). "Some examples are PTPN11 that is known to activate a transcriptional program associated with cancer stem cells or the EMT-related genes SOX4 or VIM that might be responsible for the high invasive capacity of the tumors and their early metastasis formation." (PMID 33706810, 2021). "In addition, previous studies have reported that amplification of SOX4 is associated with cancer progression." (PMID 34442467, 2021). "Additionally, high expression of SOX4 is associated with poor prognosis in leukemia, bladder, and breast cancers." (PMID 34442467, 2021). "In contrast, the high expression of SOX4 may be associated with a more favorable disease course in other types of cancer." (PMID 31110513, 2019). "SOX4 is a protein with diverse functions and has been implicated in multiple cancers." (PMID 20419098, 2010). "Moreover, we found that high expression of SOX4 was associated with poor prognosis in most cancer types, suggesting that SOX4 may play an important role in multiple cell types of the TME." (PMID 40624675, 2025). "SOX4, a transcription factor frequently overexpressed in HCC and other cancers, has been linked to drug resistance and poor prognosis; however, the underlying molecular mechanisms remain unexplored." (PMID 41484064, 2026). "SOX4 is a transcription factor involved in embryonic development and cell differentiation, and its function as an oncogene in various cancers has been reported." (PMID 39851970, 2025). "Studies have shown that in various cancers SOX4 activates the TGF-β signaling pathway to induce the EMT of cancer cells, thus maintaining the stemness characteristics of cancer cells." (PMID 40296912, 2025). "Measurements of MDA, Fe2+, and GSH levels in cancer cells revealed that SOX4 knockdown enhanced ferroptosis, while ChREBP overexpression partially reversed this enhancement." (PMID 40399256, 2025). "We also analyzed the differential expression of Sox4, E2f1, Trpv4 and Trim6, which are the genes important for cancer stem cell behavior and function." (PMID 40568073, 2025). "Several stemness markers have been associated with cancer stemness and tumorigenesis in UC, including Oct4, CD133, SOX4, ALDH1A1, and components of the HH signaling pathway." (PMID 40892739, 2025). "p-value < 0.05) markers previously shown to be regulators of cancer cell stemness (SOX4, RAB13, EZH2)." (PMID 41373578, 2025). "Elevated levels of SOX4, DDIT3, and GADD45A—genes implicated in stress response, DNA repair, and cancer stem cell maintenance—further suggest engagement of transcriptional mechanisms linked to cancer progression, therapy resistance, and recurrence." (PMID 40756515, 2025).
cancer (continued). "We compared the differences in SOX4 expression among the 33 cancers in TCGA and found that its expression level was significantly greater than that in normal tissues in most cancer types, but there was greater heterogeneity in its prognostic significance." (PMID 40624675, 2025). "Previous research has suggested that SOX4 can induce EMT in various cancers, promoting aggressive invasion." (PMID 39349443, 2024). "A consensus has been reached on the prognostic significance and cancer-promoting effect of SOX4 in NSCLC, but its downstream targets and specific mechanisms need to be further clarified." (PMID 39349443, 2024). "The SOX family includes total of 20 members, and the family is divided into nine subgroups that range from SOXA to SOXH SOX4 is one of the members widely studied in relation to cancer." (PMID 39052126, 2024). "We found that DEGs, such as CDKN1C, NEDD4L, PLK2 and SOX4, were closely related to the occurrence and development of malignant tumors." (PMID 38520027, 2024). "A number of studies have demonstrated that SOX4 knockdown reduces the tumorigenesis and metastasis of cancer cells." (PMID 39052126, 2024). "Regarding cancer studies, Sox4 overexpression has been reported in several types of cancer, including PAC." (PMID 39118797, 2024). "Various miRNAs in NSCLC cells can target SOX4 and inhibit migration and invasion, as well as epithelial-to-mesenchymal transition in cancer cells, further demonstrating that SOX4 is a complete regulator of malignancies." (PMID 39052126, 2024). "In summary, we identified overexpression of CD24, CTNNB1, and SOX4 signatures in CRC, revealing their association in promoting tumorigenic properties, cancer stemness, and resistance to therapy." (PMID 38203779, 2024). "SRY-box transcription factor 4 (SOX4), a crucial transcription factor, has been found to play a key role in the development of various cancers." (PMID 39349443, 2024). "It is intriguing that the only SOX4 whole gene duplication reported to date was identified in a boy with dysmorphisms and paediatric cancer (neuroblastoma), although this CNV was of paternal inheritance." (PMID 38397148, 2024). "Multiple studies have demonstrated the transcriptional effects of SOX4 in various cancer progressions." (PMID 39349443, 2024). "SOX4 is an essential developmental transcription factor that regulates stemness, differentiation, progenitor proliferation, and cancer cell proliferation." (PMID 36817577, 2023). "YTHDF2 mediated the degradation of FENDRR and promoted cancer cell proliferation by increasing SOX4 expression in EEC." (PMID 37478120, 2023). "To further validate the results of SOX4 in above pan-cancer analysis and LIHC, we analyzed the role of SOX4 knockdown in lenvatinib-treated LIHC cells in vitro." (PMID 37958409, 2023). "Studies have also shown that SOX4 plays a crucial role in the tumorigenesis of several cancers such as triple-negative breast, colorectal, liver cancers, and prostate cancers." (PMID 37904207, 2023). "For example, RhoA/ROCK and JUNB signaling pathways or SOX4 overexpression, which control NFIX expression both during embryonic development and in the context of cancer, have been linked to oxidative stress." (PMID 36901722, 2023). "Previous studies have reported that the expression of SOX4 is up-regulated in all major cancer types, including lung, bladder, prostate, hepatic, hematopoietic cancers, as well as in OS." (PMID 37904207, 2023). "The newly identified miR-3195/SOX4 axis has shed new light on the miRNA-based regulatory mechanisms involved in cancer progression." (PMID 37904207, 2023). "SOX4 is a carcinogenic gene that enhances stemness, cancer cell migration, metastasis, epithelial–mesenchymal transition, survival, and angiogenesis." (PMID 36987665, 2023). "The promoter analysis of the SOX4 transcriptional network has been established in different cell types, including cancer and neural crest cells." (PMID 37375678, 2023).
cancer (continued). "For instance, miR-88 suppresses the proliferation, migration and invasiveness of pediatric OS; miR-88 also induced apoptosis in this cancer and exerts these effects by targeting SOX4." (PMID 37904207, 2023). "A growing body of evidence has substantiated that SOX4 expression is positive in various human cancers and is responsible for tumorigenesis." (PMID 35294319, 2022). "In different cancers like lung, breast, and ovarian, SOX4 has been described as an oncogene involves in multiple tumorigenesis and progress pathways, overlaps with Wnt, PI3K, and TGF‐β signaling." (PMID 35924788, 2022). "MMA is sufficient to endow cancer cells with migratory and invasive capacity by inducing SOX4 expression by activating autocrine TGFβ signaling." (PMID 35656023, 2022). "Key genes that contribute to gliogenesis but also contribute to stemness in GBM: Notch (cancer stem cells), Sox9, Sox4, and SHH." (PMID 35538578, 2022). "Upregulated SOX4 expression participates in cancer progression, including proliferation, invasion, and migration." (PMID 35800365, 2022). "SOX4 is a common transcription factor that has been recognized to play an oncogenic role in cancers." (PMID 35442158, 2022). "To further validate these findings, we examined the PIK3C2B and SOX4 transcriptional levels upon YAP/TAZ siRNA knockdown in different cancer cell lines." (PMID 36347861, 2022). "The fundamental roles of TGFβ signaling in cancer metastasis has been attributed to its ability to foster cancer stemness, as exemplified by the elevated SOX4 expression in gastric cancers sustained by TGFβ over-activation." (PMID 36551308, 2022). "SRY-related high-mobility-group box 4 (SOX4) is a common transcription factor overexpressed in diverse kinds of malignant tumors." (PMID 35294319, 2022). "SOX4 has also been shown to regulate TUBB3 expression cancer, and this will be discussed in a subsequent section." (PMID 35573698, 2022). "We found that ac4C peaks in the genes associated with the cancer pathway (BCL9L), the cell cycle (AKT1) and stem cell maintenance (SOX4) decreased in the NAT10 knockdown UMUC‐3 cells." (PMID 35522942, 2022). "The overall level of SOX4 in patients with advanced cancer was much higher than that in patients in early stages." (PMID 35522942, 2022). "These progenitor cancer cells presented alterations of key transcription factors such as SOX4 (SRY-Box Transcription Factor 4), SOX11 (SRY-Box Transcription Factor 11), and TCF4 (Transcription Factor 4)." (PMID 35875065, 2022). "In WT mice, GEM responses are driven by metabolic regulators (primarily lipid metabolism), while in Rag1KO mice, CPA and GEM responses are driven by chemical drivers, and cancer associated drivers were inhibited (MYC, SOX4, MYB)." (PMID 35309309, 2022). "Among the more than 20 members of the SOX family, SOX11 and SOX4 have been shown to play important roles as targets of mir211 in a variety of cancers." (PMID 35912006, 2022). "Mechanistically, hsa_circ_0020714 induces the immune evasion of NSCLC cells via sponging miR-30a-5p to upregulate SOX4 expression, which has been confirmed acted as a oncogene in several malignant tumors, including NSCLC." (PMID 35800365, 2022). "We then validated the recurrence of carcinoma precursor cell population in our biopsy slides by probing their specific marker genes SOX4 and REG4, which are involved in carcinogenesis." (PMID 35221332, 2022). "Among these TFs, we found various TFs functioned in cancer/normal stem-like cells such as Sox4, Foxo3 and Myc, indicating their potential regulation on BCSC heterogeneity." (PMID 34675206, 2021). "SOX4 consensus normalized expression value (NX) and SOX4 protein transcripts per million (pTPM)—described by The Human Protein Atlas—are seven to eight times higher in cancer cells originating from the B line compared to the B lymphocytes." (PMID 34945712, 2021).